NEAT1 (nuclear paraspeckle assembly transcript 1)
Diseases named in the same sentence as NEAT1 in open-access papers (continued):
Sharing a sentence is not in itself a finding about the gene and the disease.
Huntington disease (continued). "In Huntington's disease, for example, neural lncRNAs are upregulated in taurine upregulated 1 (TUG1) and in nuclear paraspeckle assembly transcript 1 (NEAT1) but are downregulated in maternally expressed 3 (MEG3)." (PMID 23843741, 2013). "There is some controversy as to whether or not NEAT1 actively contributes to Huntington’s disease pathogenesis or if it triggers neuroprotective mechanisms." (PMID 30717168, 2019).
liver cancer (24 papers, 2017 to 2025). An epithelial or non-epithelial malignant neoplasm that arises from the liver. "NEAT1 overexpression is an independent risk factor related to the prognosis of liver cancer patients." (PMID 38374893, 2024). "This study investigated the effects of a long noncoding RNA, nuclear paraspeckle assembly transcript 1 (NEAT1) variant 1 (NEAT1v1) on drug resistance in liver cancer cell lines." (PMID 36826016, 2023). "A study of whole-genome mutational landscape of liver cancer also discovered mutations in lncRNA NEAT1 and MALAT1." (PMID 31338259, 2019). "Our findings also suggested that NEAT1 was associated with mechanotransduction in liver cancer." (PMID 34769497, 2021). "In particular, stiffer matrices enhance the expression of the long noncoding RNA (lncRNA) NEAT1, notoriously involved in liver cancer progression." (PMID 40282211, 2025). "Other ceRNAs that are associated with EMT in TNBC include HOTAIR (HOX transcript antisense intergenic RNA), HULC (Highly upregulated in liver cancer) and NEAT1 (Nuclear paraspeckle assembly transcript 1), all promoting a mesenchymal phenotype." (PMID 39272915, 2024). "In liver cancer, lncRNA NEAT1 increases autophagy by controlling miR-204/ATG3 and increases cell resilience to sorafenib." (PMID 37790613, 2023). "Anti-mTOR ChIP assay detected strong mTOR binding to the promoter region of NEAT1 promoter in a rapamycin-sensitive manner in human liver cancer cells." (PMID 35547764, 2022). "Collectively, our observations reveal that NEAT1 expression/paraspeckle biogenesis is a key determinant for the success of mTORC1-targeted cancer therapy in liver cancer." (PMID 35547764, 2022). "To further investigate the function of NEAT1 in the progression of liver cancer, we analyzed RNA binding proteins (RBPs) using an online database." (PMID 34769497, 2021). "In contrast, the serum expression of NEAT1 was significantly increased in colorectal, gastric, prostate, and liver cancer." (PMID 33670447, 2021). "To explore how substrate stiffness impacts liver cancer cell fate and the expression of NEAT1, we built a model of 3D topological micropillars." (PMID 34769497, 2021). "Nonetheless, this is the first report showing that NEAT1 participates in mechanotransduction in liver cancer." (PMID 34769497, 2021). "We have previously shown that this tendency towards creation of novel Ets binding motifs is found in other gene promoters, like BCL2 in lymphoma or NEAT1 in liver cancer." (PMID 31109337, 2019). "They found that NEAT1 presented at a lower level of expression in liver cancer tissue than in normal tissue, which was consistent with our result based on the 57 microarray and RNA-seq datasets." (PMID 28118609, 2017). "AKT phosphorylation decreased in liver cancer cell lines knocked down for NEAT1." (PMID 36826016, 2023). "Furthermore, SA‐β‐Gal activity, p16 and p19 (p14 in human) were up‐regulated in liver cancer tissues of the Neat1−/− mice compared with WT littermates." (PMID 37752791, 2023). "In liver cancer cell lines, NEAT1 or SOD2 knockdown activates the PERK/EIF2α pathway." (PMID 36826016, 2023). "Neat1 is also involved in liver cancer via activation of the Wnt/β-catenin pathway." (PMID 35966937, 2022). "In liver cancer cells, NEAT1 promotes growth through modulating ATGL expression." (PMID 34769497, 2021). "Therefore, our findings provide evidence that ECM-derived mechanical signals regulate cell proliferation and drive EMT through a NEAT1/WNT/β-catenin mechanotransduction pathway in the tumor microenvironment of liver cancer." (PMID 34769497, 2021). "In conclusion, NEAT1 regulated the EMT process by binding to YB1 in liver cancer." (PMID 34769497, 2021). "Thus, this study aimed to explore how NEAT1 senses tissue stiffness and regulates liver cancer metastasis." (PMID 34769497, 2021). "Nevertheless, the detailed molecular mechanism of NEAT1 function in liver cancer remains elusive." (PMID 34769497, 2021).
liver cancer (continued). "Consistent with our observations in vitro, silencing of NEAT1 significantly attenuated tumor volumes and mitigated tumor weight relative to the control group, suggesting that silencing of NEAT1 inhibits liver cancer growth." (PMID 34769497, 2021). "LncRNA NEAT1 could regulate proliferation, apoptosis, and invasion of liver cancer." (PMID 35300348, 2022). "However, whether and how NEAT1 senses and regulates the mechanical properties of liver cancer tissue is currently unresolved." (PMID 34769497, 2021). "We found that NEAT1 knockdown and NEAT1v1 overexpression resulted in the downregulation and upregulation, respectively, of SOD2 in liver cancer cells." (PMID 36826016, 2023). "To evaluate the role of NEAT1 in mTORC1-dependent aerobic glycolysis, liver tumor development and therapy in vivo, we generated mAKT/NRAS-driven mouse liver cancer by hydrodynamic transfection (HDT) in the absence or presence of shNeat1_2." (PMID 35547764, 2022). "To explore the ECM stiffness of liver cancer to impact EMT and the expression of NEAT1, we built 3D micropillar structure models." (PMID 34769497, 2021). "Several examples have been reported in HCC, such as the lncRNA highly upregulated in liver cancer (HULC), MALAT1, and nuclear enriched abundant transcript 1 (NEAT1)." (PMID 29495592, 2018). "Interestingly, it was recently shown that NEAT1 overexpression can induce stemness via the canonical Wnt/β-catenin pathway, suggesting as ECM properties can influence liver cancer progression." (PMID 40282211, 2025). "It is suggested that NEAT1/BAIAP2-AS1-ITGAV-hsa-miR-542-3p and MAPKAPK5-AS1-ITGAV-hsa-miR-450b-5p axis may be involved in the process of liver cancer." (PMID 38374893, 2024). "For example, BANCR can be used as a potential therapeutic target for liver neoplasms, NEAT1 is necessary for liver neoplasm marker CD44 expression, and LINC00473 promotes the progression of liver cancer by acting as microRNA-195 ceRNA and increasing HMGA2 expression." (PMID 35058974, 2021). "Enhanced NEAT1 expression can activate the WNT/β-catenin signaling pathway, and then the WNT/β-catenin signaling pathway contributes to the EMT process and promotes tumor proliferation in liver cancer." (PMID 34769497, 2021). "Thus, we identified the NEAT1-WNT/β-catenin pathway as regulating EMT and tumor metastasis in the liver cancer mechanical microenvironment." (PMID 34769497, 2021). "To identify how and whether the interaction between NEAT1 and YB1 contributed to liver cancer, we overexpressed YBX1 in NEAT1-KD HepG2 cell lines." (PMID 34769497, 2021). "This study elucidated the mechanisms of substrate stiffness-induced NEAT1 regulation of the EMT process through activating the WNT/β-catenin pathway in HepG2 cells, suggesting that the NEAT1-WNT/β-catenin pathway may potentially serve as a target for the clinical therapy of liver cancer." (PMID 34769497, 2021). "Finally, TIA1′s interaction with lncRNAs, e.g., MALAT1 and NEAT1, which display oncogenic features in HCC, likely also contributes to the tumor-suppressive effect of TIA1, since we could show that TIA1 silencing promotes NEAT1 upregulation in hepatic cancer cells." (PMID 35406476, 2022). "Furthermore, nuclear paraspeckle assembly transcript 1 (NEAT1) was identified as a matrix stiffness-responsive long non-coding RNA (lncRNA) regulating proliferation and EMT in response to increasing matrix stiffness during the progression of HepG2 cells towards liver cancer phenotypes." (PMID 34769497, 2021).
osteosarcoma (24 papers, 2018 to 2025). A usually aggressive malignant bone-forming mesenchymal neoplasm, predominantly affecting adolescents and young adults. "lncRNA NEAT1 (nuclear enriched abundant transcript 1) epigenetically suppresses E-cadherin expression in osteosarcoma cells by association with the G9a–DNMT1 (DNA methyltransferase 1)—SNAIL complex." (PMID 31947678, 2020). "NEAT1 causes its tumorigenic effect by enhancing osteosarcoma cell viability when treated with cisplatin." (PMID 35582574, 2019). "It was reported that NEAT1 promotes chemotherapeutic resistance in osteosarcoma by reducing the level of miR-34c and causing a decrease in cell cycle arrest via enhanced Bcl-2 and cyclin D1 expression." (PMID 35582574, 2019). "The tissue-specific abundance of these ceRNAs, for instance, lncRNA NEAT1 is high in osteosarcoma but low in testes, creates different activity thresholds for miR-483." (PMID 41463366, 2025). "For instance, lncRNA–miRNA axes such as MEG3/miR-664a and TUG1/miR-144-3p have been mechanistically linked to OS progression; knockdown of the oncogene lncRNA NEAT1 restores the availability of miR-34c and delays the tumor growth in osteosarcoma." (PMID 41331461, 2025). "For instance, in osteosarcoma, lncRNA NEAT1 competitively binds miR-483, relieving miR-483-mediated inhibition of STAT3, thereby promoting epithelial–mesenchymal transition (EMT) and metastasis." (PMID 41463366, 2025). "lncRNA NEAT1 (nuclear enriched abundant transcript 1) is another oncogenic transcript involved in the osteosarcoma metastasis and EMT regulation." (PMID 35755302, 2022). "NEAT1 in macrophages played a proinflammatory role while inhibiting inflammation in osteosarcoma cells, suggesting that the specific target cell type needs to be considered when targeting NEAT1." (PMID 35335994, 2022). "Prior work has documented that lncRNA NEAT1 expression was enhanced in the context of osteosarcoma, suggesting its oncogenic role in human cancers." (PMID 35184134, 2022). "Using this mechanism, NEAT1 finely restrains the expression of miR-483 and promotes the proliferation and migration of osteosarcoma cells." (PMID 33546665, 2021). "In summary, these results confirmed that NEAT1 promoted the EMT of osteosarcoma cells by upregulating STAT3 expression and increasing its phosphorylation, which was mediated by the inhibition of miR-483 expression." (PMID 33546665, 2021). "Taken together, NEAT1 promoted the liver and lung metastases of osteosarcoma in vivo through the miR-483/STAT3 axis." (PMID 33546665, 2021). "The overexpression of NEAT1 provokes EMT, whereas EMT is abrogated by NEAT1 silencing in osteosarcoma cells." (PMID 34298879, 2021). "The NEAT1/miR-483/STAT3 axis identified in the present study played a crucial role in modulating the EMT in osteosarcoma cells, and a similar axis with different miRNAs as the mediator has been shown to participate in the progression of various tumours." (PMID 33546665, 2021). "Several studies on the role of NEAT1 in OS progression showed that upregulation of NEAT1 in osteosarcoma tissues promoted OS cell proliferation, migration, and invasion, EMT, and inhibited cell apoptosis." (PMID 34512157, 2021). "The lncRNA NEAT1/miR-483/STAT3 axis plays a crucial role in regulating the metastasis of osteosarcoma and potentially represents one appealing therapeutic target for osteosarcoma treatment in the future." (PMID 33546665, 2021). "In this section, we summarize and discuss the role of the NEAT1/miRNA/target axis in osteosarcoma, a type of mobility system tumor." (PMID 34512157, 2021). "The primary tumour volume progression data revealed a slower growth rate of osteosarcoma derived from sh-NEAT1-transfected U2OS cells than tumours derived from sh-NC-transfected U2OS cells (p < 0.01 at day 14, 21, 28, 35, 42, respectively)." (PMID 33546665, 2021).
osteosarcoma (continued). "Nuclear enriched abundant transcript 1 (NEAT1) is an important regulator of cell functions and can adjust growth and metastasis of tumors in osteosarcoma." (PMID 33023572, 2020). "Overexpression of NEAT1 markedly accelerated proliferative and reduced apoptosis potentials of osteosarcoma cells." (PMID 31044561, 2019). "To confirm the cellular localization of NEAT1, we isolated osteosarcoma cells into cytoplasmic and nuclear fractions, with GAPDH and U6 as controls, respectively." (PMID 31044561, 2019). "Then, CCK‐8 assay indicated that NEAT1 downregulation markedly decreased the proliferative ability of osteosarcoma cells." (PMID 31044561, 2019). "QRT‐PCR data revealed that miR‐34a‐5p expression was lower in osteosarcoma tissues, which was contrary to the expression trend of NEAT1." (PMID 31044561, 2019). "Our study showed a higher expression of NEAT1 in osteosarcoma cells relative to normal osteoblast cells." (PMID 31044561, 2019). "We then examined the relative expression of NEAT1 in osteosarcoma cells (Saos2,MG63, U2OS, SJSA1, and HOS) and human normal osteoblast cells hFOB1.19 by qRT‐PCR." (PMID 31044561, 2019). "In particular, HOS cells expressed the highest level, while Saos2 cells expressed the lowest level of NEAT1 among the selected osteosarcoma cell lines, which were chosen for the subsequent experiments." (PMID 31044561, 2019). "lncRNA NEAT1 sponges miR‐186‐5p and promotes the progression of osteosarcoma invasion and EMT." (PMID 36059626, 2022). "Like with other cancers, NEAT1 represents a sinister predictor for a poor outcome in osteosarcoma." (PMID 35893235, 2022). "Consequently, NEAT1 is yet another promising target in the treatment of metastatic osteosarcoma via epigenetic-derived therapeutics." (PMID 35755302, 2022). "Since miR-483 was a target of NEAT1, we speculated that NEAT1 might promote the EMT of osteosarcoma cells." (PMID 33546665, 2021). "Moreover, NEAT1 silencing inhibited the mesenchymal- epithelial transition (MET) of osteosarcoma at metastasis sites." (PMID 33546665, 2021). "Overall, this evidence substantiated the hypothesis that the lncRNA NEAT1 promotes the EMT of osteosarcoma cells by sponging miR-483." (PMID 33546665, 2021). "Additionally, the in vivo growth of osteosarcoma was noticed to be significantly hampered by NEAT1 silencing." (PMID 34298879, 2021). "However, the specific mechanism of NEAT1 involvement in osteosarcoma development still needs to be explored." (PMID 31044561, 2019). "To elucidate whether NEAT1 regulated HOXA13 expression via targeting miR‐34a‐5p, we detected expression levels of HOXA13 in osteosarcoma cells after altering NEAT1 or miR‐34a‐5p expressions." (PMID 31044561, 2019). "The biological role of NEAT1 in the pathological process of osteosarcoma has been pointed out." (PMID 31044561, 2019). "Our results verified that NEAT1 was highly expressed in osteosarcoma tissues." (PMID 31044561, 2019). "Taken together, these results indicate that NEAT1 may exert regulatory effects on apoptosis and proliferative potentials of osteosarcoma cells." (PMID 31044561, 2019). "The results showed that NEAT1 was highly expressed in osteosarcoma tissues." (PMID 31044561, 2019). "We may conclude that NEAT1 participates in the development of osteosarcoma through post‐transcriptional regulation." (PMID 31044561, 2019). "Therefore, explorations on the effect of NEAT1 on accelerating growth of osteosarcoma cells are of great significance for in‐depth studies of the occurrence and development of osteosarcoma." (PMID 31044561, 2019). "NEAT1 overexpression accelerated the proliferative rate of osteosarcoma cells." (PMID 31044561, 2019). "We believed that both NEAT1 and miR‐34a‐5p may participate in the development and progression of osteosarcoma." (PMID 31044561, 2019). "Our results demonstrated a high expression of NEAT1 in osteosarcoma tissues and cells." (PMID 31044561, 2019).
osteosarcoma (continued). "In this study, NEAT1 expression in osteosarcoma cells was detected by qRT‐PCR." (PMID 31044561, 2019). "Additionally, the prognostic value of NEAT1 expression was determined for overall survival in osteosarcoma patients by the Kaplan–Meier analysis, suggesting that high expression level of NEAT1 is significantly correlated with shorter overall survival." (PMID 31044561, 2019). "NEAT1 expression in osteosarcoma tissues and paired paracancerous tissues was detected by qRT‐PCR." (PMID 31044561, 2019). "LncRNA NEAT1 expression remains high in osteosarcoma tissues." (PMID 31044561, 2019). "Given that NEAT1 was primarily located in the cytoplasmic fraction, we hypothesized that NEAT1 may act as a ceRNA in the development of osteosarcoma." (PMID 31044561, 2019). "In addition, cell apoptosis experiment showed that overexpression of NEAT1 reduced the apoptosis capacity of osteosarcoma cells, and NEAT1 downregulation induced the apoptosis capacity of osteosarcoma cells." (PMID 31044561, 2019). "In addition, downregulation of NEAT1 expression remarkably reduced proliferative and induced apoptosis capacities, suggesting that NEAT1 was an important regulator in the growth of osteosarcoma cells as an oncogene." (PMID 31044561, 2019). "However, the clinical significance and function of NEAT1 in osteosarcoma (OS) remain to be discovered." (PMID 29654165, 2018). "However, further studies are needed to elucidate whether NEAT1 and miR-483 participate in the mechanism regulating the biological behaviour of osteosarcoma cells through other signalling pathways, which will be further explored in our future studies." (PMID 33546665, 2021). "Our study demonstrated that miR‐34a‐5p was downregulated in osteosarcoma cells, and transfection with miR‐34a‐5p mimics promoted apoptosis and suppressed proliferative capacities of osteosarcoma cells, which could be reversed by NEAT1 overexpression." (PMID 31044561, 2019). "The knockdown of NEAT1 in transplanted U2OS cells impaired the liver and lung metastases of osteosarcoma in nude mice." (PMID 33546665, 2021). "Their high expression predicted poor prognosis of osteosarcoma (MALAT1 (HR = 2.15, 95%CI: 1.67–2.76, P < 0.001), TUG1 ((HR = 2.41, 95%CI: 1.42–4.07, P = 0.001), XIST (HR = 1.79, 95%CI: 1.40–2.30, P < 0.001), NEAT1 (HR = 1.96, 95%CI: 1.05–3.68, P = 0.035))." (PMID 33639865, 2021). "Based on our data, strategies targeting NEAT1 with small molecule inhibitors or siRNAs will potentially interfere with both the MET and EMT processes during the metastasis of osteosarcoma." (PMID 33546665, 2021). "Afterwards, control shRNA (sh-NC)-transfected or NEAT1 KD U2OS cells were subcutaneously injected into the left outer flank of BALB/c nude mice to establish liver and lung metastases of osteosarcoma." (PMID 33546665, 2021). "NEAT1 KD significantly impaired both the EMT and MET processes in primary tumours and metastatic tumours respectively during the metastasis of osteosarcoma, indicating versatile roles for NEAT1." (PMID 33546665, 2021). "We also used the Starbase database to predict potential targets of NEAT1 and ascertain its role in regulating the EMT of osteosarcoma cells." (PMID 33546665, 2021). "Overall, these findings suggest that NEAT1 and TUG1 are attractive targets for osteosarcoma therapy." (PMID 34298879, 2021). "Accordingly, our study verified that upregulated NEAT1 increased expression of HOXA13, the target gene of miR‐34a‐5p, further leading to abnormal proliferation and apoptosis of osteosarcoma cells." (PMID 31044561, 2019). "NEAT1 induced osteosarcoma cell proliferation and cell mobility by binding to miR-339-5p and increasing TGF-β1 in osteosarcoma." (PMID 31214487, 2019). "Although our study is not the first study reporting the association between NEAT1 and miR-483, it describes the regulation of STAT3 by miR-483 and their functions in regulating the EMT and metastasis of osteosarcoma cells for the first time." (PMID 33546665, 2021).